SH2B1 (SH2B adaptor protein 1)
Diseases named in the same sentence as SH2B1 in open-access papers (continued):
Sharing a sentence is not in itself a finding about the gene and the disease.
metabolic disease (10 papers, 2011 to 2025). A congenital disorder (due to inherited enzyme abnormality) or acquired (due to failure of a metabolically important organ) disorder resulting from an abnormal metabolic process. "Both BDNF and SH2B1 have been implicated in metabolic diseases." (PMID 24260264, 2013). "Interestingly, both SH2B1 and BDNF are obvious candidate genes for metabolic disorders based on the biological roles of the encoded proteins." (PMID 21912638, 2011).
tumor (8 papers, 2016 to 2025). "Knockdown of BBOX1-AS1 inhibited the progression of CRC cell, including cell proliferation, migration, invasion and conversely promoted apoptosis of tumor cells by sponging miR-361-3p/SH2B1 regulatory axis." (PMID 35842644, 2022). "In a previous study, we had observed that SH2B1 was significantly upregulated in NSCLC tissues and cell lines, and high SH2B1 expression was associated with tumor size." (PMID 30202243, 2018). "In multiple malignancies including NSCLC, the up-regulation of SH2B1 is positively correlated with tumor TNM stages and poor survival rate." (PMID 30202243, 2018). "Most notably, overexpression of SH2B1 in H1299 cells (H1299-SH2B1) significantly increased the tumor growth rate and tumor mass in vivo." (PMID 30202243, 2018). "One recent study found that in nonsmall cell lung cancer (NSCLC), miR-361-3p could suppress tumor cell proliferation and metastasis by directly targeting SH2B1." (PMID 30344797, 2018). "The tumor-suppressive role of miR-361-3p is largely mediated by one of its target, Sh2B1." (PMID 27164951, 2016). "The tumor-promoting effect of SH2B1 may be partially related the activations of Akt/mTOR/PTEN axis." (PMID 30202243, 2018). "SH2B1, a member of the SH2-domain containing family, have recently been shown to act as tumor activators in multiple cancers." (PMID 30202243, 2018). "Furthermore, miR‐3126‐5p, SH2B1, and IRS1 levels were elevated, but KLF13 level was reduced in tumours of Exos‐treated mice, whereas KLF13 overexpression counteracted these changes, except change in miR‐3126‐5p expression." (PMID 41410190, 2025). "Additionally, silencing of KLF13 raised the protein levels of SH2B1, IRS1, GLUT1, PDK1, and LDHA in xenograft tumours, and KLF13 overexpression exhibited the reverse actions." (PMID 41410190, 2025). "SH2B1, one member of the SH2B family, has been documented to serve as tumor activators in cancers." (PMID 31417870, 2019). "One previous study found that miR-361-3p might act as a tumor suppressor in NSCLC and its antioncogenic activity may be due to its inhibition of the target gene SH2B1." (PMID 30344797, 2018). "The SH2B1/Akt/mTOR/PTEN axis is required for regulating NSCLC cell proliferation and might prove to be a promising strategy for restraining tumor progression in NSCLC patients." (PMID 30202243, 2018). "miR-361-3p functions as a novel tumor suppressor in NSCLC and the anti-oncogenic activity may involve its inhibition of the target gene SH2B1." (PMID 27164951, 2016). "In addition, upregulation of p‐AKT in Exos‐treated tumours was reversed by BKM120, whereas downregulation of KLF13 and upregulation of miR‐3126‐5p, SH2B1, IRS1, and p‐PI3K caused by Exos were not affected by BKM120 co‐administration." (PMID 41410190, 2025).
cancer (7 papers, 2016 to 2025). A tumor composed of atypical neoplastic, often pleomorphic cells that invade other tissues. "More recently, SH2B1 has been linked to the progression of cancer, including lung, esophageal, gastric, and oropharyngeal cancers." (PMID 39897164, 2025). "Moreover up-regulation of SH2B1 protein was found in various types cancer and high SH2B1 expression is associated with more aggressive phenotypes." (PMID 27164951, 2016). "Although SH2B1 is highly expressed in these cancers and serves as an indicator of poor prognosis, the exact function of SH2B1 in tumors is not yet clear." (PMID 39897164, 2025). "However, in cancer process, the adaptor protein SH2B1 is rarely well characterized." (PMID 30202243, 2018). "Moreover, for four types of cancer (KIRP, UVM, CESC, and LUSC), patients in the high-expression level group for SH2B1 gene experienced a better prognosis than those in the low/medium-expression level group." (PMID 33299884, 2020). "Not surprisingly, in cancer cells activation of RET oncogenic signaling, which can be induced and enhanced by SH2B1, can override growth suppressor (RET inhibitors) activities and stimulate cell cycle progression and further potentiates the neoplastic transformation." (PMID 30202243, 2018).
SH2B1 also shares sentences with these, for which no sentence is quoted: Hyperglycemia (5 papers); Hyperinsulinemia (4); Bardet-Biedl syndrome (2); hyperlipidemia (2); Hypertension (2); Monogenic obesity (2); schizophrenia (2); type 1 diabetes (2); alcohol dependence (1); Alzheimer disease (1); asthma (1); attention deficit-hyperactivity disorder (1); blood pressure (1); cardiovascular diseases (1); endocrine disease (1); hyperuricemia (1); infection (1); inflammatory bowel disease (1); keratinization disorder (1); liver cancer (1); microcephaly (1); mood disorder (1); Non-Alcoholic Fatty Liver Disease (1); Noonan syndrome (1); obesity syndromes (1); oesophageal cancer (1); pancreatic cancer (1); Phelan-McDermid syndrome (1); prostate carcinoma (1); psoriasis (1).
A further 5 diseases each share a sentence with SH2B1 in 1 paper.